MAVS (mitochondrial antiviral signaling protein)
Diseases named in the same sentence as MAVS in open-access papers (continued):
Sharing a sentence is not in itself a finding about the gene and the disease.
ZIKV infection (14 papers, 2017 to 2025). "In contrast, and in the setting of maternal immunocompetence, mitochondrial antiviral-signaling (MAVS) protein-dependent type I IFN signaling in the fetus was found to be necessary to restrict ZIKV infection in the fetal compartment of the placenta." (PMID 40401980, 2025). "In contrast, Zika virus infection stimulates the RIG-I/MAVS/IRF3 pathway and downstream IFN-β expression, which increases HLA expression in infected cells." (PMID 32321802, 2020). "To further elucidate the physical interaction between NS4A and MAVS, we also performed an endogenous IP assay upon ZIKV infection." (PMID 31183075, 2019). "Since both RIG-I and MDA5 contribute to the type I IFN responses to ZIKV infection, blocking MAVS is more energy-efficient than inhibiting individual RIG-I and MDA5 separately." (PMID 29988497, 2018). "In the ZIKV infection/polyI:C stimulation conditions, MAVS needs to be activated by RIG-I/MDA5 binding to its CARD domain, which can be blocked by NS4A." (PMID 29988497, 2018). "Hsp70 is also in association with DNAJB1, which is known to mediate cellular RNA sensing by interacting with MDA5/MAVS that could be validated for ZIKV infection in future studies." (PMID 30866755, 2019). "Since MAVS signaling is essential for inducing an IFN production during ZIKV infection, it is plausible that viruses may hijack this important host response to facilitate infection of the host." (PMID 31183075, 2019). "The deletion of RIG-I significantly inhibited the LDH release and the activation of GSDME, as well as its upstream caspase-3 and caspase-8 during ZIKV infection, while the KO of MDA5 or MAVS only slightly suppressed this process." (PMID 35972780, 2022). "Knockout of either RIG-I or MDA5 reduced, while deletion of the common adaptor for both RIG-I and MDA5, MAVS, almost completely abolished type I IFN induction and supports productive ZIKV infection." (PMID 29988497, 2018). "Consistent with the replication data, we found that RIG-I KO cells and cells lacking MAVS produced virtually no IFN-λ upon ZIKV infection." (PMID 33658344, 2021). "Our observations that ZIKV infection induces an antiviral state in moDCs, despite viral antagonism of type I IFN responses, further suggests IFN-independent signaling pathways, such as RLR signaling through MAVS, are important for restriction of ZIKV replication." (PMID 28152048, 2017). "MAVS and IRF3 mice did not experience weight loss, morbidity, or mortality, suggesting that MAVS and IRF3 might not be required for the antiviral response to ZIKV infection in mice." (PMID 38137537, 2023). "Interestingly, we found that KO of MAVS, a downstream molecule of RIG-I, only slightly reduced the cleavage of GSDME, which indicates the possibility that ZIKV infection leads to the placental pyroptosis via the non-canonical RIG-I pathway." (PMID 35972780, 2022).
HIV-1 infection (13 papers, 2011 to 2025). The type species of lentivirus and the etiologic agent of acquired immunodeficiency syndrome (AIDS). "The results showed that individuals carrying the G allele at MAVS rs16989000 had a significantly higher probability of HIV-1 infection compared to those carrying the A allele (p = 0.049, OR = 1.197, 95% CI 1.001–1.433)." (PMID 40331958, 2025). "Here, we investigated the underlying mechanism responsible for the effect of this MAVS genetic variation on the control of HIV-1 infection." (PMID 32708557, 2020). "Notably, individuals with the GC genotype at MAVS rs17857295 present an elevated risk of HIV-1 infection compared to those with the CC genotype." (PMID 40331958, 2025). "The results revealed significant association between five SNPs (NLRP3 rs4612666, MAVS rs17857295, MAVS rs6084497, MAVS rs16989000, and JAK1 rs4244165) and HIV-1 infection." (PMID 40331958, 2025). "In vitro HIV-1 infection of peripheral blood mononuclear cells (PBMCs) from healthy donors with the MAVS minor genotype resulted in decreased viral replication." (PMID 32708557, 2020). "Interestingly, while MAVS protein levels were unaffected by MAVS genetic variation, in vitro infection of PBMCs from healthy individuals with a MAVS minor genotype resulted in decreased viral replication levels, indicating that these cells are less susceptible to HIV-1 infection and replication." (PMID 32708557, 2020). "This study shows that four MAVS SNPs affect HIV-1 infection and the progression of AIDS." (PMID 40331958, 2025). "However, we found a marked decrease in MAVS levels after HIV-1 infection at both 3 and 7 dpi, as compared to their respective uninfected controls." (PMID 41041557, 2025). "Our data suggest that the protective effect of the MAVS minor genotype is associated with control of HIV-1 infection in CD4+ T cells in the PBMC culture, rather than by an intrinsic restriction in CD4+ T cells." (PMID 32708557, 2020). "Indeed, macrophages and DCs present in PBMCs from MAVS minor donors may exert a DDX3-induced MAVS-mediated type I IFN response upon in vitro HIV-1 infection, which can interfere with virus replication in the CD4+ T cells." (PMID 32708557, 2020). "Yet, SERINC5 has been shown to enhance MDA5-mediated IFN signaling, and SERINC5 can interact with MAVS and TRAF6 to inhibit HIV-1 infection." (PMID 36223419, 2022). "No changes were found in the mRNA expression levels of MAVS or TRAF3 genes after HIV-1 infection for 3 or 7 dpi when compared with uninfected control cultures." (PMID 41041557, 2025). "The mitochondrial antiviral protein MAVS signals downstream of MDA5 and DDX3, serving as a platform for TBK1/IKKE activation, and is therefore able to elicit the antiviral type I IFN and cytokine responses needed to combat HIV-1 infection." (PMID 39665545, 2025). "The mitochondrial antiviral protein MAVS signals downstream of RIG-I and DDX3 and serves as a platform for TBK1/IKKɛ activation, thus containing the potency to elicit antiviral type I IFN and cytokine responses needed to combat HIV-1 infection." (PMID 32708557, 2020). "Despite the central role of MAVS in viral RNA-mediated interferon induction and innate and adaptive immune responses, MAVS stimulation has not been studied in the context of HIV-1 infection." (PMID 26849062, 2016). "Transient knockdown of MAVS, STING, or UNC93B1 did not affect HIV-1 infection establishment, as quantified by p24Gag production in the culture supernatants, compared to non-targeted (scramble) control." (PMID 40920844, 2025).
autoimmune disease (10 papers, 2015 to 2025). A disorder resulting from loss of function or tissue destruction of an organ or multiple organs, arising from humoral or cellular immune responses of the individual to their own tissue constituents. "Additionally, spontaneous aggregation of MAVS has been reported to be associated with autoimmune diseases." (PMID 36028484, 2022). "Accumulating evidence has demonstrated the pivotal roles of MAVS in multiple biological processes, including pathogen invasion and autoimmune diseases (e.g., SLE and psoriasis)." (PMID 39621307, 2024). "However, when second signals are scarce and weak, such as in the early stages of an autoimmune disease, MAVS deficiency could significantly impact B cell activation and renders “protection” to disease development, as observed in MAVS and FcγR2b double deficient mice." (PMID 37610299, 2023). "The de-repression of ERVs and the activation of RIG-I/MDA5/MAVS pathway were observed during neurodegeneration, cancer, aging and autoimmune diseases." (PMID 35757716, 2022). "Among pathways upstream of MAVS, multiple genetic studies have linked functional alterations of MDA5 with autoimmune disorders in humans and mice." (PMID 31681326, 2019). "Conversely, BST-2 helps prevent excessive immune responses—which could lead to autoimmune diseases—by mediating the degradation of mitochondrial antiviral signaling protein (MAVS) or restricting the production of LINE-1 RNA." (PMID 39917304, 2025). "The distinct functions of ZDHHC12-mediated palmitoylation in regulating the NLRP3 inflammasome and MAVS-mediated antiviral innate immunity may help balance immune responses and prevent autoimmune diseases." (PMID 39621307, 2024). "Also, our results indicate ZDHHC7 as a potential therapeutic target for MAVS-related autoimmune diseases." (PMID 39141356, 2024). "Hence, we rationalized that PRMT9 could inhibit the autoactivation of MAVS in unstimulated cells, which may be a potential mechanism for a host to avoid autoimmune diseases." (PMID 36028484, 2022). "However, spontaneous aggregation of MAVS can lead to autoimmune diseases." (PMID 36028484, 2022). "Since we revealed that ZDHHC7 increases MAVS oligomerization and enhances type I interferon production, inhibition of ZDHHC7 might be a therapeutic strategy alleviating these autoimmune diseases." (PMID 39141356, 2024).
Autoimmunity (9 papers, 2012 to 2025). The occurrence of an immune reaction against the organism's own cells or tissues. "To better understand how MAVS deficiency prevents autoimmunity in Fcgr2b-deficient mice, we focused on B cell activation because previous data implicated a B cell–intrinsic effect." (PMID 37610299, 2023). "And mutations or dysregulation of MAVS have been implicated in a variety of diseases, including autoimmune disorders." (PMID 37122709, 2023). "Excessive activation of MAVS-mediated antiviral signaling leads to dysfunction of mitochondria and cell apoptosis that likely causes the pathogenesis of autoimmunity." (PMID 23308066, 2012). "On the other hand, activation of MAVS has been implicated in some autoimmune disorders." (PMID 30326919, 2018). "Excessive activation of MAVS-mediated antiviral signaling leads to dysfunction of mitochondria as well as cell apoptosis, which likely lead to the pathogenesis of autoimmunity." (PMID 30326919, 2018). "This study supports the role of MAVS in B cell activation with implications in autoimmunity." (PMID 37610299, 2023). "In summary, we have uncovered anti-viral independent roles for MAVS in regulation of autoimmunity." (PMID 31681326, 2019). "However, our data points to a TLR7-independent role of MAVS in the development of autoimmunity." (PMID 31681326, 2019). "Contrasting the essential role for MAVS in B cell autoimmunity, we found no such role for the cytoplasmic DNA sensor STING, also known to induce type I IFN." (PMID 31681326, 2019). "However, despite the efficient MAVS-dependent innate immune response, NZB.3d mice were found to be protected from systemic autoimmunity even when persistently infected with LCMV." (PMID 30199535, 2018).
colitis (9 papers, 2012 to 2024). Inflammation of the colon. "RIG-I deficient mice spontaneously develop a colitis–like phenotype, and RIG-I, Nalp3 or Mitochondrial antiviral signalling protein (MAVS) deficient mice exhibit susceptibility to DSS-induced colitis with varying levels of severity." (PMID 34188111, 2021). "Consistent with a role for MAVS in NLRP3 activation, MAVS-deficient mice exposed to dextran sodium sulphate (DSS)-induced colitis fail to upregulate IL-1β." (PMID 29120406, 2017). "For example, RIG-I/MAVS-dependent signaling may be stimulated by RNA derived from commensal enteric bacteria to protect against experimentally induced colitis." (PMID 39352770, 2024). "MAVS monitors intestinal commensal bacteria and induces an immune response that plays a dominant role in maintaining tissue homeostasis and protection against colitis." (PMID 30326919, 2018). "Previous studies have proposed a protective function of IFN-I in the setting of allo-HSCT and of stromal MAVS signaling in a dextran sodium sulfate (DSS)–induced mouse model of colitis, but the mechanisms by which IFN-I contributes to this protection remain ill defined." (PMID 28424327, 2017). "Mice lacking the mitochondrial protein MAVS (also known as IPS-1, VISA or CARDIF), which is an essential adaptor protein in the RLR pathway, are highly sensitive to experimental colitis in part because of defective immune response to commensal bacterial RNA." (PMID 23110254, 2012).
lung carcinoma (9 papers, 2018 to 2025). "Human lung cancer NCI‐H358 (H358) cells showed significant up‐regulation of DDX58, MDA5, MAVS, IRF7, IFNB, RSAD2, and ISG56, after incubation with immRNA‐loaded RBCEVs." (PMID 35430766, 2022). "Degradation of the mitochondrial antiviral-signaling protein (MAVS) is another way to enhance mitophagy in order to attenuate the antiviral immune response, as shown in measles virus infection in lung cancer cells." (PMID 32967329, 2020). "In our model system based on lung cancer cell lines, we found that the ability of DIP co-infection to reduce the C′-mediated lysis of PIV5-infected cells was not changed when the host cell had a genetic knockout of the key IFN-I component MAVS." (PMID 40284931, 2025). "Taken together, our data suggest that MAVS expression (or ADAR1-mediated MAVS editing) in DLBCL (as opposed to other solid tumors such as lung cancer) is positively correlated with inflammation cascade and exhaustion status of the tumor-infiltrating T cells." (PMID 37255666, 2023). "Our data show that MDA5/MAVS signaling is not essential for ADAR genetic dependency in lung cancer cell lines." (PMID 30575730, 2018).
melanoma (9 papers, 2016 to 2025). A malignant, usually aggressive tumor composed of atypical, neoplastic melanocytes. "Further study showed that PSV inhibited the production of IFN-β by cleaving mitochondrial antiviral signaling (MAVS) and degrading melanoma differentiation-associated gene 5 (MDA5) and TANK-binding kinase 1 (TBK1) through viral 3Cpro." (PMID 35782136, 2022). "In summary, Our study identified USP35 as a novel negative regulator of the MAVS-mediated type I interferon signaling pathway in malignant melanoma cells." (PMID 40016186, 2025). "Currently, ZDHHC4 has been shown to functionally affect the palmitoylation and activation of MAVS in the murine B16 melanoma cell line." (PMID 39621307, 2024). "Currently, ZDHHC4 has been shown to functionally affect the palmitoylation of MAVS in murine B16 melanoma cells." (PMID 39621307, 2024). "When viewed in combination, these studies demonstrate that the spread of malignant melanoma is associated with decreased expression of essential components of the RLH pathway and heightened expression of the RLH/MAVS inhibitor NLRX1." (PMID 27198666, 2016). "However, R.E treatment reprograms melanoma cellsto produce IFN, potentially through MAVS signaling associated withMDA5." (PMID 41341044, 2025). "Thus, our collaborative research with W. Sheng’s team has shed light on the functional roles of ZDHHC12 in human and murine macrophages and ZDHHC4 in murine B16 melanoma cells, revealing their ability to promote MAVS-mediated immune responses." (PMID 39621307, 2024). "Notably, ZDHHC4 has been demonstrated to enhance MAVS-mediated immune responses in murine B16 melanoma cells." (PMID 39621307, 2024). "Mechanistically, σ3 inhibits RIG-I and melanoma differentiation-associated gene 5 expression is independent of its inhibitory effect on MAVS." (PMID 38757961, 2024). "Specifically, they demonstrate that Poly(I:C)-induced RLH activation inhibits melanoma and other metastasis via a MAVS-dependent mechanism and that the melanoma inhibitory effects of Poly(I:C) are associated with the induction of Type I IFNs and dependent on IFNAR1." (PMID 27198666, 2016). "In contrast, the melanoma inhibitory effects of Poly(I:C) were abrogated in the absence of MAVS." (PMID 27198666, 2016). "Using CRISPR-Cas9 edited loss of function variants of the human melanoma cell line 1205Lu, we confirmed that in the experimental system used in this study, the early induction of interferon-stimulated cytokines by VSV is RIG-I- and MAVS-dependent but does not require MDA5 or PKR." (PMID 33995343, 2021).
breast carcinoma (7 papers, 2012 to 2025). "For example, circPVT1 is highly expressed in breast cancer and promotes breast cancer development by targeting both ESR1 mRNA and MAVS protein." (PMID 37723588, 2023). "However, when looking at the correlation between TET2 expression and antiviral response genes in breast cancer patients, a positive correlation was found only for EIF2AK2, MAVS, OTUD4, ABCE1, and RNase L expression levels." (PMID 35351824, 2022).
Flavivirus Infections (7 papers, 2017 to 2025). Infections with viruses of the genus FLAVIVIRUS, family FLAVIVIRIDAE. "Although deficiency of RIG-I, MDA5 or MAVS in HEK293 cells only modestly increased the levels of YFV RNA, the RLR pathway has been shown to play a critical role in the control of flavivirus infection and immunopathogenesis in vivo." (PMID 35061864, 2022). "While this, to our knowledge, has not been reported before, a non-trivial interaction and cooperation between IRF3, -7, and -5 downstream of MAVS has been observed in flavivirus infection of dendritic cells." (PMID 34685580, 2021). "STING, another viral sensor highly expressed in DCs, potentiates RIG-I-mediated antiviral signaling in response to flavivirus infection by directly interacting with RIG-I and MAVS." (PMID 31242236, 2019).
ovarian carcinoma (7 papers, 2020 to 2023). A malignant neoplasm originating from the surface ovarian epithelium. "The present study evaluates the value of mitochondrial antiviral signaling (MAVS) expression as a potential diagnostic biomarker and therapeutic target for ovarian cancer (OC) and analyses the underlying biological mechanism in this pathology." (PMID 34722508, 2021). "A previous study reported that ovarian cancer (OC) with high MAVS expression was remarkably less responsive to cisplatin and paclitaxel than those with low MAVS expression." (PMID 37901251, 2023). "In the present study, we identified MAVS as a potential indicator for predicting the prognosis of OC based on 128 ovarian cancer tissues by IHC." (PMID 34722508, 2021). "Weighted gene co-expression network analysis was applied to explore the co-expression network of MAVS in ovarian cancer." (PMID 34722508, 2021). "IHC staining indicated that MAVS expression was positive in 62 cases, accounting for 48.4% of ovarian cancers." (PMID 34722508, 2021). "In the present study, a predictive model of commonly used chemo drugs in ovarian cancer was performed to investigate whether patients with positive MAVS expression are more sensitive to chemotherapy." (PMID 34722508, 2021). "Although little is known about the upregulation mechanisms of these pathways in the MAVS-positive expression group, MAVS may influence the prognosis of ovarian cancer by regulating these pathways." (PMID 34722508, 2021). "The representative images of IHC staining of MAVS on tissue microarray of ovarian cancer specimens." (PMID 34722508, 2021). "In the MAVS-positive expression group, the Notch pathway, Hh pathway, and Wnt pathway were upregulated, which have been demonstrated to be related to chemotherapy resistance in ovarian cancer." (PMID 34722508, 2021). "The expression of MAVS in 128 ovarian cancer tissues was examined by immunohistochemistry (IHC)." (PMID 34722508, 2021). "The correlation heat map of MAVS expression with immune infiltration levels in ovarian cancers revealed that CD8+ T cells, gamma delta T cells, and eosinophils had a significantly negative correlation with MAVS expression." (PMID 34722508, 2021).